ZNF593OS (ZNF593 opposite strand)
Synonyms: ZNF593-AS
Gene: Protein-coding gene on chromosome 1 (26,169,516 to 26,171,832, reverse strand). Ensembl gene ENSG00000236782.
Subcellular location: Membrane
Gene Ontology:
Cellular component: membrane
Homologues: Orthologues: chimpanzee ZNF593OS (98% identical), macaque ZNF593OS (98% identical), rabbit ZNF593OS (89% identical), dog ZNF593OS (87% identical), rat Zfp593os (87% identical), mouse Zfp593os (86% identical), pig ZNF593OS (86% identical).